CLU (clusterin)
Diseases named in the same sentence as CLU in open-access papers (continued):
Sharing a sentence is not in itself a finding about the gene and the disease.
Insulin resistance (17 papers, 2014 to 2026). Increased resistance towards insulin, that is, diminished effectiveness of insulin in reducing blood glucose levels. "This metabolic setting renders the exploration of novel biomarkers linked to inflammation, insulin resistance, and lipid metabolism disorders therapeutically significant; one molecule of interest in this regard is CLU." (PMID 41515662, 2026). "Correspondingly, previous clinical data implicated that circulating clusterin (a) correlates closely with insulin resistance and (b) decreases in line with improving insulin sensitivity in type 2 diabetes." (PMID 36553017, 2022). "In sum, WC was positively associated with insulin resistance, dyslipidemia, inflammation and clusterin (the indirect marker of oxidative stress)." (PMID 33905632, 2021). "Thus, on the one hand, Clusterin is positively associated with metabolic parameters, such as glycosylated hemoglobin A1c, insulin resistance by HOMA-IR, and fasting C-peptide levels, and has been proposed as a communicator between adipocytes and the liver." (PMID 36553017, 2022). "Clusterin can bind insulin, and its deficiency exacerbates insulin resistance in T2D77." (PMID 35383192, 2022). "In addition, polymorphisms in CLU have been linked to insulin resistance [by the homeostasis model of insulin resistance [HOMA-IR] and impaired insulin secretion [HOMA-β]]." (PMID 33717095, 2021). "Low clusterin levels in HDL were associated with insulin resistance and may play a role in the loss of HDL’s protective functions." (PMID 32235466, 2020). "Secretory clusterin is also known as ApoJ which has recently been identified as a novel hepatokine and deletion of hepatic ApoJ leads to insulin resistance and glucose tolerance." (PMID 34391409, 2021). "Circulating IL-6, clusterin and irisin may represent possible therapeutic targets for insulin resistance in obese subjects." (PMID 33905632, 2021). "Although, chronic inflammation remains the main mechanism triggers insulin resistance, adipose tissue produces both pro- and anti-inflammatory substances including IL-6, clusterin and irisin which may play a role in glucose hemostasis." (PMID 33905632, 2021). "In this context, circulating IL-6, clusterin and irisin may represent possible therapeutic targets for insulin resistance in obese subjects." (PMID 33905632, 2021). "Loss of clusterin (CLU) is associated with NIDDM and insulin resistance." (PMID 30678306, 2019). "Although these results suggest several mechanisms by which clusterin could link insulin resistance, metabolic disease, and CVD, further investigation is needed to fully elucidate the cardiometabolic role of AT clusterin, and specifically clusterin derived from the adipocyte." (PMID 33717095, 2021). "Clusterin in HDL is related to insulin sensitivity, whereas clusterin in LDL is closely correlated with insulin resistance." (PMID 36553017, 2022). "Clusterin can also directly affect insulin signaling and inflammation, two factors that can lead to insulin resistance, via its actions on macrophage phosphoinositide 3-kinase (PI3K; a mediator of insulin signaling) and NFκB (a major pro-inflammatory pathway in insulin resistance)." (PMID 33717095, 2021).
metabolic syndrome (17 papers, 2014 to 2026). A cluster of metabolic risk factors for CARDIOVASCULAR DISEASES and TYPE 2 DIABETES MELLITUS. "Clusterin is a chaperone protein that binds lipids such as high- and low-density lipoproteins and has been implicated in metabolic syndrome; it can also be citrullinated and is elevated in patients with early RA." (PMID 37899440, 2023). "In summary, the circulating clusterin levels were significantly associated with the parameters for adiposity and systemic inflammation and increased in subjects with metabolic syndrome." (PMID 25076422, 2014). "A second class consisted of carrier proteins such as apolipoprotein M (APOM), apolipoprotein C1 (APOC1), and clusterin (CLU), which play important roles in cholesterol metabolism and are likely to be associated with cirrhosis‐related dyslipidemia due to reduced liver biosynthesis capacity." (PMID 30824564, 2019). "In addition to BMI, we found in our current analysis that the fasting clusterin levels were associated with markers of visceral adiposity, a principal metabolic syndrome component." (PMID 25076422, 2014). "In support of these identified mechanistic processes, both murine and human studies have demonstrated a significant link between circulating clusterin and features of the metabolic syndrome." (PMID 33717095, 2021). "Conversely, metabolic syndrome was found to be more common in subjects in the highest plasma clusterin quartile." (PMID 25076422, 2014). "Sex-stratified analysis also revealed a tendency of increase in circulating clusterin levels in individuals with metabolic syndrome." (PMID 25076422, 2014). "Sex-stratified analysis also displayed a tendency of increased clusterin levels in subjects with metabolic syndrome." (PMID 25076422, 2014). "As triglycerides are key components of the metabolic syndrome, elevated clusterin may indicate improved lipid transport and metabolism to preserve a metabolic homeostasis and cardioprotection." (PMID 36553017, 2022). "The aim of the present study is to contribute to the elucidation of pathophysiological links between psoriasis, its pro-inflammatory comorbidity metabolic syndrome (MetS), and the expression of clusterin and elafin, which are reflected in the pathophysiological “portfolio” of both diseases." (PMID 32764517, 2020). "Although both psoriasis and metabolic syndrome were associated with the elevation of clusterin levels, the presence of the combination of diseases did not elevate the expression of clusterin, compared to psoriasis alone." (PMID 32764517, 2020). "Furthermore, plasma clusterin levels showed an upward trend with increasing numbers of metabolic syndrome components." (PMID 25076422, 2014). "Since metabolic syndrome accompany low-grade chronic inflammation, our findings may suggest that plasma clusterin levels reflect systemic meta-inflammation." (PMID 25076422, 2014). "Moreover, plasma clusterin concentrations were higher in the subjects with metabolic syndrome and increased with the number of metabolic syndrome parameters." (PMID 25076422, 2014). "Furthermore, plasma clusterin levels showed an upward trend with increased metabolic syndrome component numbers." (PMID 25076422, 2014). "Furthermore, higher number of metabolic syndrome components correlated with the higher plasma clusterin levels." (PMID 25076422, 2014). "Metabolic syndrome and smoking was more prevalent in men than in women, which may contribute to the increased circulating clusterin levels in men." (PMID 25076422, 2014). "Therefore the findings of this study may provide the basis for understanding the role of clusterin in subjects with low-grade chronic inflammation such as in metabolic syndrome." (PMID 25076422, 2014). "Our data indicate that CLU levels were markedly higher in the PCOS group relative to healthy persons, as well as in patients with metabolic syndrome within the PCOS subgroup." (PMID 41515662, 2026).
metabolic syndrome (continued). "CLU levels were significantly higher in women with metabolic syndrome in the PCOS cohort compared to those without." (PMID 41515662, 2026). "Plasma clusterin levels were higher in subjects with metabolic syndrome than in those without metabolic syndrome." (PMID 25076422, 2014). "The subjects in our study cohort with metabolic syndrome showed higher circulating clusterin levels compared with those without metabolic syndrome." (PMID 25076422, 2014).
coronary heart disease (16 papers, 2009 to 2025). "Although altered plasma clusterin concentrations have been reported in patients with coronary heart disease, the pathophysiological mechanism underlying these alterations and the association with KD remains unknown." (PMID 23956692, 2013). "Microarray analysis in female subcutaneous adipocytes found that CLU gene expression was upregulated in obese versus lean patients, and serum levels of gene CLU was elevated during T2D and coronary heart disease." (PMID 35568907, 2022). "Studies in humans and mice have identified clusterin in atherosclerotic plaques of the aorta, and clusterin levels were reported to correlate with serum paraoxonase and apolipoprotein B concentrations in Japanese men and women with coronary heart disease." (PMID 29534716, 2018). "Lastly, coexpression network analysis was undertaken on smoking-related hub genes of coronary heart disease in GeneMANIA, and then, ITGA2B, ALOX12, ESLP, and CLU were acquired." (PMID 35096131, 2022). "CLU expression was not higher in diabetic patients or in patients suffering from coronary artery disease." (PMID 24758255, 2014).
glioma (15 papers, 2014 to 2025). A benign or malignant brain and spinal cord tumor that arises from glial cells (astrocytes, oligodendrocytes, ependymal cells). "Collectively, these findings demonstrate a positive association between CLU expression and glioma in patients." (PMID 40606578, 2025). "Bioinformatics analyses showed that CLU was highly expressed in glioma, associated with poor clinical outcomes." (PMID 40606578, 2025). "According to the expression profiles in TCGA, we found that CLU expression was associated with the tumor grades of gliomas, with markedly higher expression in GBM than in LGG." (PMID 37686218, 2023). "We found that CLU expression was associated with glioma grades, with higher expression levels in GBM than in LGG." (PMID 37686218, 2023). "High CLU expression (hazard ratio of 1.451) and high glioma grades (hazard ratio of 3.145) were identified as two risk factors for prognosis of LGG patients." (PMID 37686218, 2023). "Given the role of CLU in apoptosis and its association with cancer progression, it is plausible that CLU may influence the malignancy of gliomas through apoptosis pathways." (PMID 40606578, 2025). "Additionally, CLU has been found to be associated with the expression of pro-inflammatory cytokines like IL-1β, which can contribute to the development of a senescent phenotype in glioma cells." (PMID 40606578, 2025). "Overall, these results demonstrate that CLU promotes glioma progression primarily by accelerating cell migration and proliferation." (PMID 40606578, 2025). "The mRNA and protein levels of CLU were consistently higher in the glioma region compared to the HC group." (PMID 40606578, 2025). "Collectively, these results demonstrate that CLU promotes glioma formation in vivo, with its effects mediated through the upregulation of BCL2L1." (PMID 40606578, 2025). "Firstly, immunofluorescence analysis revealed that CLU protein levels were significantly higher in glioma regions compared to peritumoral regions." (PMID 40606578, 2025). "Silencing CLU reduced the migration and proliferation of glioma cells, while overexpression of CLU enhanced these aggressive phenotypes." (PMID 40606578, 2025). "Compared to healthy controls (HC), CLU mRNA expression was significantly elevated in patients with lower-grade glioma (LGG, WHO grades II and III) and glioblastoma (GBM, WHO grade IV)." (PMID 40606578, 2025). "CLU expression has been found to be significantly upregulated in gliomas compared to normal brain tissue." (PMID 40606578, 2025). "The elevated expression of CLU in gliomas suggests its potential role in tumor progression and malignancy." (PMID 40606578, 2025). "To further investigate the role of CLU in glioma, we conducted a series of experiments using various glioma cell lines." (PMID 40606578, 2025). "This discussion focuses on the role of clusterin in gliomas, particularly its expression patterns, and prognostic significance, as well as its potential as a therapeutic target." (PMID 40606578, 2025). "In summary, our study provides compelling evidence that CLU plays a significant role in glioma progression by enhancing cell migration and proliferation, while inhibiting apoptosis primarily through the upregulation of BCL2L1." (PMID 40606578, 2025). "CLU, a glycoprotein involved in cell survival and apoptosis resistance, is commonly overexpressed in several cancers and gliomas." (PMID 40573993, 2025). "To elucidate the potential role of CLU in glioma, we examined its expression in glioma tissues using immunofluorescence on pathological brain samples from patients with glioma." (PMID 40606578, 2025). "Collectively, these results suggest that CLU accelerates cell migration and growth while inhibiting apoptosis in glioma cell lines primarily through the upregulation of BCL2L1." (PMID 40606578, 2025). "By silencing CLU, glioma cells lose a major defense against apoptosis, thereby becoming more vulnerable to treatments that promote cell death." (PMID 40573993, 2025).
glioma (continued). "Elevated CLU expression in glioma tissues correlates with advanced tumor grades and poorer patient survival, highlighting its potential as a prognostic biomarker." (PMID 40606578, 2025). "Collectively, these in vivo results demonstrate that CLU promotes glioma formation, with its effects mediated through the upregulation of BCL2L1." (PMID 40606578, 2025). "Inhibiting BCL2L1 reversed the pro-migratory and pro-proliferative effects of CLU overexpression and restored apoptosis in glioma cells." (PMID 40606578, 2025). "Further analysis of CLU mRNA expression in a database showed elevated levels in patients with lower-grade glioma (LGG) and glioblastoma (GBM) compared to healthy controls (HC)." (PMID 40606578, 2025). "This study comprehensively investigated the role of CLU in glioma progression by examining its expression in glioma tissues and cell lines, as well as its impact on tumor formation in vivo." (PMID 40606578, 2025). "Our research has found that CLU is upregulated in glioma and contributes to increased tumor malignancy." (PMID 40606578, 2025). "Consistent with this, our previous study also observed similar effects in promoting senescence in gliomas following CLU silencing." (PMID 40573993, 2025). "The fluorescence intensity of CLU protein was significantly higher in the glioma region compared to the peritumoral region, suggesting a possible promoting role of CLU in glioma progression." (PMID 40606578, 2025). "First, expression of CLU in gliomas and its correlations with clinicopathologic features and prognosis were investigated." (PMID 37686218, 2023). "This study will provide evidence for the roles of CLU in gliomas and its potential to be a prognostic biomarker or therapeutic target in gliomas." (PMID 37686218, 2023). "To this end, we conducted this study to conduct a comprehensive investigation on the roles of CLU in gliomas." (PMID 37686218, 2023). "In conclusion, this was the first study to investigate the expression and specific roles of CLU in gliomas." (PMID 37686218, 2023). "In gliomas, CLU expression was markedly elevated in tumor tissue than in normal tissue, and immunohistochemical staining of CLU in clinical samples verified the high expression of CLU in tumor tissue." (PMID 37686218, 2023). "To this end, we designed this study to conduct a comprehensive investigation on the roles of CLU in gliomas in terms of three major aspects." (PMID 37686218, 2023). "In conclusion, CLU appears to play crucial roles in tumor immunity within gliomas, highlighting its potential as a biomarker or target in glioma immunotherapy." (PMID 37686218, 2023). "In central nervous system tumors, CLU has been observed to exhibit high expression levels in pituitary adenomas compared to its expression in non-neoplastic adenohypophyses." (PMID 37686218, 2023). "Downregulation of CLU has been shown to inhibit cell proliferation and induce cellular senescence in astrocyte cells, suggesting that CLU may play a role in maintaining the viability and growth of glioma cells." (PMID 40606578, 2025). "In vivo experiments confirmed the inhibitory effects of CLU downregulation on glioma growth." (PMID 40606578, 2025). "By inducing cellular senescence through CLU silencing, this treatment strategy could suppress glioma cell growth and improve prognosis and outcomes for glioma patients." (PMID 39627493, 2025). "Analysis of glioma patient data revealed a positive correlation between CLU and BCL2L1 expression." (PMID 40606578, 2025). "Based on these data, targeting CLU may serve as a potential therapeutic approach valuable for treating gliomas." (PMID 39627493, 2025). "Recent studies have revealed that CLU is involved in the progression of gliomas." (PMID 40606578, 2025). "Interestingly, CLU deficiency caused senescence and mitochondrial dysfunction in the CCF-STTG1 glioma cell line, known for its high-grade and aggressive characteristics, as well as in immortalized human astrocytes." (PMID 40573993, 2025).